IL4 (interleukin 4)
Diseases named in the same sentence as IL4 in open-access papers (continued):
Sharing a sentence is not in itself a finding about the gene and the disease.
experimental autoimmune encephalomyelitis (33 papers, 2007 to 2026). An autoimmune demyelinating disease of the central nervous system that is produced experimentally in animals by the injection of homogenized brain or spinal cord in Freund's adjuvant. "IL-4′s role in regulating inflammation within the CNS was demonstrated in the experimental autoimmune encephalomyelitis (EAE), an animal model of MS, in which mice deficient in IL-4 exhibited more severe EAE clinical disease." (PMID 34769314, 2021). "Here, we report that DKO TH2-high carrying autoantigen-specific TCR (2D2) develop atypical spontaneous experimental autoimmune encephalomyelitis (EAE), with CD4+ T cells simultaneously producing IL-4 and GM-CSF, directly causing neuroinflammation." (PMID 41577662, 2026). "Studies on experimental autoimmune encephalomyelitis (EAE) have shown that the formation of IL4 within the CNS is necessary to control autoimmune inflammation within the CNS." (PMID 37626706, 2023). "Hence, it has been reported that in VPAC2-deficient mice with experimental autoimmune encephalomyelitis, proinflammatory cytokines (TNF-α, IL-6, IFN-γ (Th1), and IL-17 (Th17)) increased, and anti-inflammatory cytokines (IL-10, TGF-β, and IL-4 (Th2)) decreased." (PMID 36101343, 2022). "Yet, IL-4 is also a key differentiating factor for wound healing macrophages, which is essential for tissue repair, and is known to oppose IL-17-mediated inflammatory diseases like psoriasis and experimental autoimmune encephalomyelitis (EAE)." (PMID 33617447, 2021). "The inhibitory effect of PPARD agonist was also found to be associated with an increase of cytokine IL-4 and IL-10 expression and decreased IL-12 and IL-23 expression in the CNS confirming the modulatory effect of PPARD agonist in experimental autoimmune encephalomyelitis." (PMID 34394070, 2021). "Combined IL-2 and IL-4 reduces the severity of experimental autoimmune encephalomyelitis (EAE)." (PMID 33617447, 2021). "Finally, interacting with the neuronal IL-4 receptor, IL-4 could mediate a protective function, inducing actin modifications and axonal sprouting, as observed in experimental autoimmune encephalomyelitis (EAE) models." (PMID 32719583, 2020). "In the case of experimental autoimmune encephalomyelitis (EAE), interleukin-4 (IL-4)-induced type 2 immunity suppresses type 1 driven inflammation, thereby ameliorating EAE." (PMID 37429945, 2023). "In experimental autoimmune encephalomyelitis (EAE), GA positively regulates inflammation by increasing anti-inflammatory IL-4, IL-10 and IL-13, while the pro-inflammatory cytokines IL-6, IL-12 and TNF-α are reduced." (PMID 36831209, 2023). "Nevertheless, the ability of DcR3 to upregulate IL-4 and IL-10 but simultaneously downregulate IFN-γ, IL-12, TNFα, and IL-17 after influenza hemagglutinin peptide stimulation and in the experimental autoimmune encephalomyelitis model was demonstrated." (PMID 33746978, 2021). "For example, in previous studies, GA was found to be protective against Experimental Autoimmune Encephalomyelitis (EAE) in Stat6–/– and IL4–/–IL10–/– mouse models." (PMID 34744620, 2021). "A study in a model of experimental autoimmune encephalomyelitis in mice found that Hypericum perforatum extract in combination with gold nanoparticles decreased levels of IFN-γ, IL-17A and IL-6 and increased those of TGF-β, IL-10 and IL-4." (PMID 37687297, 2023).
myocardial infarction (33 papers, 2017 to 2025). Gross necrosis of the myocardium, as a result of interruption of the blood supply to the area, as in coronary thrombosis. "Adult mice with Il4 or Il13 deficiency experienced tissue repair impairment following myocardial infarction as judged by reduced accumulation of reparative macrophages." (PMID 38093747, 2023). "Neonatal Il4- and Il13-deficient mice showed impaired cardiac function after myocardial infarction when compared with gene-proficient mice." (PMID 38093747, 2023). "In the heart, the critical contribution of IL-4- and IL-13-activated macrophages to cardiac repair was reported: Trib1-deficient mice that selectively lack IL-4-associated macrophages frequently experienced cardiac rupture after myocardial infarction." (PMID 36016937, 2022). "However, in a recent publication that explored the mechanisms associated with wound healing following experimental myocardial infarction (MI), basophils were identified as a critical source of IL-4/IL-13 required for the healing process." (PMID 36578500, 2022). "Both LPS-induced pro-inflammatory polarized macrophage and IL-4-induced anti-inflammatory polarized macrophage are known to promote angiogenesis in mouse hindlimb ischemia and myocardial infarction models." (PMID 39707436, 2024). "On the other hand, recombinant IL-4 improved myocardial tissue repair after myocardial infarction in a mouse model." (PMID 39091640, 2024). "In vivo studies have demonstrated that administration of IL-4 in mice post-myocardial infarction (MI) selectively augments the population of M2-like macrophages." (PMID 38727300, 2024). "LPS and IL-4 function in a concerted way to alleviate mouse myocardial infarction by mediating Sirpα." (PMID 39707436, 2024). "In the study, compared to the first day of myocardial infarction, there was an increase in the titers of interleukin 4 and interleukin 10, obtained 30 days after myocardial infarction, but the titers of IL-6 did not change overtime." (PMID 35837017, 2022). "There was an increase in the titers of IL-4 and IL-10 at D30 after myocardial infarction compared to D1 (P=0.013 and P<0.001, respectively, Wilcoxon test), while IL-6 titers did not change (P=0.31, Wilcoxon test)." (PMID 33495783, 2021). "Alternatively, activated M2 macrophages induced by IL-4 stimulation are involved in cardiac repair after myocardial infarction." (PMID 32265926, 2020). "Our results were confirmed in a very recent study in a myocardial infarction model, where overexpression of Nox4 promoted M(IL4+IL13) polarization of cardiac macrophages and protects from postinfarction remodeling." (PMID 31178956, 2019). "It is pointed out that interleukins such as IL-1, IL-4, IL-6, and IL-8 are involved in the development of myocardial infarction, most of which are released into the circulation and serve as inflammatory biomarkers, and these effects were also reflected in our results." (PMID 34957234, 2021). "In addition, IL-4 administration increases the number of reparative macrophages and enhances the post-myocardial infarction prognosis in mice." (PMID 30333983, 2018). "This translational study thus aimed to investigate whether IL-4 administration is useful for the treatment of myocardial infarction." (PMID 28761077, 2017). "Serum levels of IL-27, IL-4, IL-17, and interferon (IFN)-γ in healthy subjects as well as patients with ACS, including stable angina pectoris (SA), unstable angina pectoris (UA), and acute myocardial infarction (AMI), were determined using an enzyme-linked immunosorbent assay." (PMID 30631648, 2019). "Some inflammatory cytokines, including IL-1, IL-4, IL-6, IL-8, IL-18, and TGF-β1, are involved in the development of ischemic heart disease, myocardial infarction, and heart failure, thus, serving as potential targets for the development of some anti-ischemic therapies." (PMID 32104703, 2020).
myocardial infarction (continued). "Furthermore, in a mouse model of myocardial infarction, TNF-α mRNA, IL-1α, IL-2, IL-4, IL-5, IL-6, IL-10, IL-17A, TNF-α, IFN-γ, and GM-CSF expression were all lower in the infarct area of TLR4-deficient mice compared with wild-type mice." (PMID 30399158, 2018). "Moreover, one study suggested that exogenous IL-4 may serve as a potential treatment for myocardial infarction (MI) by promoting reparative connective tissue formation in the infarct area, but not pathological interstitial fibrosis, potentially via an impact on macrophage function." (PMID 37949903, 2023).
osteoarthritis (31 papers, 2006 to 2026). A noninflammatory degenerative joint disease occurring chiefly in older persons, characterized by degeneration of the articular cartilage, hypertrophy of bone at the margins and changes in the synovial membrane. "IL-4 is associated with M2 macrophages and inducing M2 polarization and is also chondroprotective in osteoarthritis." (PMID 40861855, 2025). "Few studies have shown that IL-4 is associated with the pathological process of osteoarthritis; accordingly, we mainly explored the expression of IL-4 and the relationship between IL-4 and SOCS1 in IL-1β-stimulated human osteoarthritic chondrocytes." (PMID 28373981, 2017). "Moreover, IL-4 protects against post-traumatic osteoarthritis in mice and down-regulates osteoarthritis-associated genes in human synovial tissue." (PMID 35625533, 2022). "Furthermore, IL-2, IL-17, IL-23, TNF-β, GM-CSF, MCP-1, RANTES, eotaxin, IL-4, IL-5, IL-10 and G-CSF are also closely related with cognitive decline with ageing, synaptic or neuronal loss, osteoarthritis cancer, lung senescence." (PMID 27105505, 2016). "Therefore, we aimed to investigate whether other anti-inflammatory mechanisms may be involved as upregulation of IL-4 and IL-10, as was recently suggested in association with treatment of acute lung injury or osteoarthritis." (PMID 26640325, 2015). "Recently, a randomized double-blind placebo-clinical trial by arthrocen showed that its oral administration diminished TNF-α and IL-17 while it increased anti-inflammatory IL-4 and IL-10 blood levels in patients with osteoarthritis." (PMID 38402151, 2024). "As a result of the induction of osteoarthritis, the serum levels of IL4 dramatically decreased compared to the healthy mice group." (PMID 37109424, 2023). "Tobetter understand the mechanisms behind its potential as DMOAD, thissystematic narrative review aims to assess the potential of IL-4, IL-10 andthe combination of IL-4 and IL-10 for the treatment of osteoarthritis." (PMID 35549461, 2022). "The IL4-10 fusion protein was further examined in in vitro as well as in vivo models of osteoarthritis and chondroprotective, anti-inflammatory, and analgesic activity of this protein was reported." (PMID 34831223, 2021). "They demonstrated that IL-2, IL-4, IL-6, and IL-10 levels were higher in patients with osteoarthritis compared to the controls." (PMID 32189997, 2020). "In an animal model of osteoarthritis, intra-articular injection of IL-4 inhibits chondrocyte production of nitric oxide and subsequent cartilage destruction." (PMID 21294892, 2011). "Ingenuity pathway analysis of male VICs with UTY-KD on blank and PS-NP gels showed strong associations to pathways related to osteoblasts and chondrocytes in inflammatory diseases, osteoarthritis signaling, and interleukin-4, interleukin-13, and interleukin-17 signaling, among others." (PMID 40073144, 2025). "Key search terms were:Osteoarthritis, Interleukin-4, and Interleukin-10." (PMID 35549461, 2022). "Various studies have demonstrated therapeutic potential for IL-4 in osteoarthritis (OA)." (PMID 33996964, 2021). "However, IL-4 was also shown to express at a decreased level in cartilage from patients with osteoarthritis compared to cartilage from healthy controls." (PMID 32189997, 2020). "Future studies on normalization or enhancement of cellular responses, e.g., gene transduction of IL-4, may provide new opportunities for the therapeutic modality of osteoarthritis." (PMID 25479057, 2014). "In another study, in osteoarthritis patients, there were significant positive correlations between ACRP-30 levels in the synovial membrane and plasma levels of IL-4, IL-1β, G-CSF, and GM-CSF." (PMID 38674217, 2024). "A fusion protein of interleukin-4 and interleukin-10 (IL4-10 FP) wasdeveloped as a disease-modifying osteoarthritis drug (DMOAD), andchondroprotection, anti-inflammation, and analgesia have been suggested." (PMID 35549461, 2022).
osteoarthritis (continued). "This study describes the production and characterization of a canine IL4-10 fusion protein (IL4-10 FP) and evaluates its in vivo DMOAD activity in a canine model of osteoarthritis (OA)." (PMID 31295306, 2019). "Recently, we developed a human fusion protein of IL4 and IL10 (hIL4-10 FP) that has DMOAD properties in multiple models of osteoarthritis." (PMID 31295306, 2019). "VCAM1 was expressed on cell surface of RA-FLSs, osteoarthritis (OA)-FLSs, or IL-4-stimulated dermal fibroblasts but not on non-stimulated dermal fibroblasts." (PMID 34281218, 2021). "The purpose of this study was to investigate the influence of moderate physical activity (MPA) on the expression of osteoarthritis (OA)-related (IL-1β, IL-6, TNF-α, MMP-13) and anti-inflammatory and chondroprotective (IL-4, IL-10, lubricin) biomarkers in the synovium of an OA-induced rat model." (PMID 30691048, 2019).
type 1 diabetes (31 papers, 2008 to 2025). "It has been shown that IL-4 has a protective effect against pancreatic beta-cell loss in type 1 diabetes and that IL-4 receptors in pancreatic beta cells are functionally competent." (PMID 38542165, 2024). "Research has shown that IL-4 protects against pancreatic β-cell loss in type 1 diabetes." (PMID 39273664, 2024). "The results of this study may support the hypothesis that a deficiency in IL-4 production by lymphocytes characterizes patients with type 1 diabetes and may contribute to the development of the disease." (PMID 36768715, 2023). "There was a lower percentage of CD3+CD4+ T lymphocytes secreting IL-4 in the study group, indicating that a deficiency in IL-4 production may be related to the development of type 1 diabetes." (PMID 36768715, 2023). "The enormous role of IL-4 may suggest that deficiency of this cytokine leads to metabolic disorders in patients with type 1 diabetes." (PMID 34830017, 2021). "In addition, we showed that the lower percentage of CD3+CD4+ T cells secreting IL-4 in patients with type 1 diabetes supports the idea that a deficiency in IL-4 production may be associated with the development of type 1 diabetes." (PMID 36768715, 2023). "For instance, n-6 PUFAs have been shown to suppress IL-4-induced increases in intestinal permeability and to protect against the onset of type 1 diabetes in antibiotic-treated mouse models." (PMID 41376027, 2025). "The percentage of CD3+CD4+ T lymphocytes with the intracellular expression of IFN-γ+, IL-2, IL-4, IL-10 and IL-17 in the patients with type 1 diabetes and in the control group was analyzed." (PMID 36768715, 2023). "The analysis of the results showed that the percentage of CD3+CD4+ T cells with intracellular expression of IL-4 was significantly lower in the patients with type 1 diabetes compared to the percentage of these cells in the control group (p = 0.004)." (PMID 36768715, 2023). "Decreased Th1 cytokines and increased CD69, PD1 and IL-4 expression were the major contributors to the segregation of adults with long-term type 1 diabetes from heathy donors." (PMID 34350463, 2021). "IL-17 and IL-4 production by MAIT cells slightly increased in individuals with long-term type 1 diabetes compared with healthy control individuals." (PMID 34350463, 2021). "Even though there was a global shift of Th1 to IL-17 and IL-4 cytokines by MAIT cells in individuals with long-term type 1 diabetes compared with healthy donors, the production of all these cytokines strongly and positively correlated with each other." (PMID 34350463, 2021). "The difference between these model systems and the NOD model of type 1 diabetes perhaps indicates that the role of the therapeutic DC in this model is to deliver high levels of IL-4 to critical areas of disease activity, such as the PLN." (PMID 20686610, 2010). "One SNP was at position 8455 on IL-4 gene, where A base pair is substituted by G. Previously this SNP g.8455A>G with Reference ID rs2243289 was found in a study conducted to find any interaction between IL-4 gene and type 1 diabetes." (PMID 36407356, 2022). "In participants with recent-onset type 1 diabetes, only IL-4 production was increased." (PMID 34350463, 2021). "Additionally, we assessed the concentrations of IFN-γ, IL-2, IL-4 and IL-10 in the plasma of individuals with type 1 diabetes and healthy group." (PMID 34830017, 2021). "Furthermore, elevated levels of IL-4 have been reported in patients with type I diabetes with hyperglycemia." (PMID 34586189, 2021). "In adults with type 1 diabetes, we found that the inflammatory cytokines IL-1α, IL-4, IL-12p70, TNF-α, and the adhesion molecule E-selectin were inversely associated with 24-hour-derived HRV parameters after adjustments for age, sex, disease duration, and smoking." (PMID 32908447, 2020).
type 1 diabetes (continued). "In participants with recent-onset type 1 diabetes, correlations were observed between HbA1c level and MAIT cell variables such as CD56+, Ki67+, GzB+ and IL-4+ MAIT cell frequencies." (PMID 34350463, 2021). "In individuals with recent-onset type 1 diabetes, Ki67+, CD56+, IL-4+ and GzB+ MAIT cell frequency positively correlated with blood HbA1c level." (PMID 34350463, 2021). "Production of IL-4+ and GzB+ is elevated in MAIT cells from children with recent-onset type 1 diabetes, although GzB+ MAIT cell frequency inversely correlates with blood HbA1c." (PMID 34350463, 2021). "In the present study, we observed that STZ-type 1 diabetes in rats induced a significant increase of plasmatic levels of IL-2 and IFN-γ (Th1 cytokines) and a decrease of IL-4 (Th2 cytokine) and IL-10 (regulatory cytokine) concentrations." (PMID 29317893, 2017). "RNF128 encodes a type I transmembrane protein located in the endocytic pathway and its expression significantly inhibited activation-induced IL4 and IL2 that are involved in type I diabetes mellitus pathway (KEGG: hsa04940)." (PMID 24344781, 2013). "Both 1,25(OH)2D3 and TX527 also reduced the Th2 cytokines IL-13 and IL-4 and IL-5 (data not shown) in cultures from control and type 1 diabetes donor T cells, albeit not always statistically significant." (PMID 25279717, 2014). "In animal studies it has been shown that extracts of soluble S. mansoni worm or eggs antigens induced secretion of anti-inflammatory cytokines including IL-10, IL-4 and IL-5 from T cells and subsequently prevented development of type 1 diabetes in non-obese mice." (PMID 35077485, 2022). "The levels of anti-inflammatory (IL-35, IL-10, IL-4) and proinflammatory (TNF-α, IL-12, IL-18) cytokines were statistically comparable between the type 1 diabetes patients with Hashimoto’s disease and those without." (PMID 39273664, 2024). "In studies of type 1 diabetes mellitus (T1DM) mouse models, exogenous supplementation of C-peptide was found to aid in the reduction of pro-inflammatory cytokines such as IL17 and tumor necrosis factor-alpha (TNFα), and anti-inflammatory cytokines, like IL4 and IL10, in the urine (P <0.05)." (PMID 37745697, 2023). "Hence, upregulating GATA-3 and IL-4 expression and downregulating T-bet and IFN-γ levels may provide a novel therapeutic method for type 1 diabetes (T1D) treatment in non-obese diabetic (NOD) mice." (PMID 36776877, 2023).